FOXP2 (forkhead box P2)
Diseases named in the same sentence as FOXP2 in open-access papers (continued):
Sharing a sentence is not in itself a finding about the gene and the disease.
Nephroblastoma (1 paper, 2022). An embryonal neoplasm characterized by the presence of epithelial, mesenchymal, and blastema components. "HOXA11-AS recruits FOXP2, positively regulates the transcription of Cyclin D2, inhibits apoptosis, and promotes cell cycle progression in nephroblastoma." (PMID 36057597, 2022).
nicotine dependence (1 paper, 2022). Physical and psychological dependence on nicotine. "For cannabis use disorder, 2 genes were significantly associated including, PDE4B (P = 2.09 × 10−6) and FOXP2 (P = 9.30 × 10−7), and one gene for nicotine dependence—ARHGAP22 (P = 2.42 × 10−6)." (PMID 36151087, 2022).
Parkinson disease (1 paper, 2015). A progressive degenerative disorder of the central nervous system characterized by loss of dopamine producing neurons in the substantia nigra and the presence of Lewy bodies in the substantia nigra and locus coeruleus. "It is tempting to postulate that, during early brain development, CD157/BST-1 expression is under FOXP2-mediated transcriptional control, which may not involve the region containing Parkinson disease-associated SNPs." (PMID 26010484, 2015).
prostate tumor (1 paper, 2023). "The fusion encodes a truncated FOXP2 mutant protein encompassing the key domains and is highly expressed in the fusion-carrying prostate tumor." (PMID 37668356, 2023). "To identify genes that are significantly regulated by FOXP2, we compared two sources of differential gene expression data from TCGA primary prostate tumors and our FOXP2-transformed NIH3T3 cells." (PMID 37668356, 2023). "(B) In the 255 primary prostate tumors shown in (A), the expression of 3206 genes was significantly correlated with the expression of FOXP2 (|Spearman’s ρ ≥ 0.5|; 1884 significantly positively correlated genes; 1322 significantly negatively correlated genes)." (PMID 37668356, 2023). "(F) Expression of FOXP2 mRNA in normal prostate samples from the GTEx dataset (n = 106) and metastatic prostate tumors from the SU2C dataset (n = 117)." (PMID 37668356, 2023). "We found that in the prostate tumor the fusion consequently resulted in increased expression of a truncated FOXP2 protein that retained the complete FOXP2 functional domains, but had an aberrant C-terminus." (PMID 37668356, 2023). "Moreover, we detected higher phosphorylation levels of MET and AKT in primary human prostate tumors with higher compared with lower FOXP2 protein abundance." (PMID 37668356, 2023). "Finally, we evaluated the clinical significance of FOXP2 copy number alterations (CNAs) in 487 primary prostate tumors." (PMID 37668356, 2023). "In this study, we identified a previously unknown intrachromosomal gene fusion involving FOXP2 in primary prostate tumors by RNA-Seq and RT-PCR combined with Sanger sequencing." (PMID 37668356, 2023). "Together, our data indicated that FOXP2 was highly expressed in human prostate tumors." (PMID 37668356, 2023). "FOXP2 activates oncogenic MET signaling in FOXP2-overexpressing cells and prostate tumors." (PMID 37668356, 2023). "We found that primary prostate tumors with FOXP2 expression had a higher Gleason grade than cases without FOXP2 expression by analyzing the clinical data of 491 human TCGA primary prostate tumors." (PMID 37668356, 2023). "In addition, we found that CNAs of FOXP2 were prominently enriched in ETS fusion-negative prostate tumors from the MSKCC/DFCI dataset (n = 685) (p=2.42 × 10–6, by Fisher’s exact test), suggesting that FOXP2 CNAs and ETS fusions were partially mutually exclusive." (PMID 37668356, 2023).
prostatic adenocarcinoma (1 paper, 2023). "Strong or medium staining of FOXP2 protein was observed in 53% (24/45) of primary prostate adenocarcinomas." (PMID 37668356, 2023). "(E) Expression of FOXP2 mRNA in 92 primary prostatic adenocarcinoma tissues and 23 matched normal tissues analyzed by qPCR." (PMID 37668356, 2023).
prostatic intraepithelial neoplasia (1 paper, 2023). "Transgenic overexpression of FOXP2 in the mouse prostate causes prostatic intraepithelial neoplasia." (PMID 37668356, 2023). "Prostate-specific overexpression of FOXP2 causes prostatic intraepithelial neoplasia." (PMID 37668356, 2023).
psoriasis (1 paper, 2021). An autoimmune condition characterized by red, well-delineated plaques with silvery scales that are usually on the extensor surfaces and scalp. "In spite that these results must be validated in vitro and in vivo with a functional genomics approach, we propose FOXP2, RUNX2, NR2F1, ELF1 and HESX1 transcription factors (those with the highest FIF on each gene) as novel drug targets for psoriasis." (PMID 33898962, 2021).
respiratory depression (1 paper, 2022). A decrease in ventilation secondary to impaired signals from the central nervous system. "Intersectional genetic targeting methods should allow investigators to determine whether the Lmx1b neurons expressing Foxp2 (KF) or Calca (PB) contribute to opioid‐induced respiratory depression." (PMID 35134251, 2022).
respiratory failure (1 paper, 2013). The significant impairment of gas exchange within the lungs resulting in hypoxia, hypercarbia, or both, to the extent that organ tissue perfusion is severely compromised. "Recent findings showed that depletion of cells with CCSP promoter activity was associated with alveolar hypoplasia and respiratory failure, adding to the idea that Ccsp downregulation as a result of Hif3α-mediated Foxp2 upregulation, directly leads to reduced numbers of Clara cells." (PMID 23451260, 2013).
sarcoma (1 paper, 2022). A usually aggressive malignant neoplasm of the soft tissue or bone. "Other transcription factors associated with DEGs identified in the present study include FOXP2 and IRX6, neither of which has been well investigated in sarcomas." (PMID 36099287, 2022).
sleep disorder (1 paper, 2020). A change from the patient's baseline sleeping pattern, in the hours slept and/or an alteration/dysfunction in the stages of sleep. "GWAS catalog analysis showed a series of previously reported sleep disorder genes, such as MEIS1, CUL9 and FOXP2 40,44,45." (PMID 32332799, 2020).
cancer (38 papers, 2015 to 2025). A tumor composed of atypical neoplastic, often pleomorphic cells that invade other tissues. "Numerous studies have associated miR-222-3p with cancer cell proliferation and apoptosis, as well as drug resistance via the suppression of FOXP2." (PMID 39057036, 2024). "Recently, critical roles of FOXP2 have been demonstrated in cancer progression as a tumor suppressor, though FOXP2 mutations are well known to cause language and speech development deficits." (PMID 31815635, 2019). "In some cancer conditions, FOXP2 levels are now considered as a critical diagnostic marker of neoplastic cells, and in many situations, they even bear strong prognostic value." (PMID 29725501, 2018). "In this study, established cancer cell lines were used as models to propose that such a low FOXP2 level was causative to their invasive capacity." (PMID 29725501, 2018). "The mutational profile in FOXP2 within cancers assembled in the Intogen database, displays an accumulation of mutations in the 7:114,270,000-114,270,020 region." (PMID 29725501, 2018). "In the following sections (“entities”) we focus upon cancer conditions associated with FOXP2 dysregulation which are supported by research articles." (PMID 29725501, 2018). "A large scale (10K+ patients) GWAS transcriptomic survey of prostate biopsies has readily associated FOXP2 levels with cancer outcome." (PMID 29725501, 2018). "Moreover, we conducted the analysis on tumors with both FOXP2 gene expression and amplification data available in the Catalogue Of Somatic Mutations In Cancer (COSMIC) datasets." (PMID 37668356, 2023). "It is revealed that FOXP2 expression was associated with the regulation of microRNAs in cancer cells and FOXP2 could inhibit the growth of cancer cells by suppressing a series of cancer stem cell associated factors." (PMID 34322159, 2021). "It has been reported that FOXP2 is associated with the development of several types of cancers." (PMID 31936744, 2020). "This suggests that aberrant FOXP2 levels may play either a pro-oncogenic or a deficient tumor-suppressor role that may be tissue-specific and vary along the progression of cancer." (PMID 29725501, 2018). "Attempts to assess whether FOXP2 transcript or protein levels can be of diagnostic relevance have been collated in cancer databases, along with individual cases reports." (PMID 29725501, 2018). "Deciphering which of these partners, such as FOXP1, CtBP1, MAPK3, GATAD2B, might be involved in oncogenic process along with FOXP2 should improve our understanding of gene networks underlying cancer progression." (PMID 29725501, 2018). "Collectively, this work suggests that FOXP2 in this cancer might belong to a small group of pro-oncogenes associated with “priming” the epithelium for cancer progression." (PMID 29725501, 2018). "Such a wide variety of targets involved in cancer suggests that dysregulated FOXP2 may cause complex interaction-dependent effects during oncogenic progression." (PMID 29725501, 2018). "A growing number of evidences have linked FOXP2 to multiple cancers and its dysregulation may play a main role throughout cancer initiation and progression, even though it may act as either a tumor-suppressor or a tumor-stimulator depending on the type of cancers studied." (PMID 33718155, 2021). "However, FOXP2 is also expressed in a large spectrum of other embryonic, postnatal and adult tissues, where its dysregulation has been observed to be associated with cancer conditions." (PMID 29725501, 2018). "Most of the recent studies investigating the roles of FOXP2 in cancer have focused on noncoding RNA-mediated dysregulation of FOXP2, suggesting that FOXP2 has either oncogenic or tumor-suppressive effects on cancer development in different tumor contexts." (PMID 37668356, 2023).
cancer (continued). "The Foxp family, which is composed of Foxp1, Foxp2, Fxop3 and Foxp4, is also involved in diverse biological processes including development, immune disorders and cancer progression." (PMID 35974052, 2022). "FOXP2, a member of the forkhead box transcription factor family, is suggested to regulate the progression of cancer cells through the epithelial–mesenchymal transition." (PMID 35893033, 2022). "This provided at least one possible mechanism of FOXP2 down-regulation in EGF-induced EMT progression in the cancer cells." (PMID 33718155, 2021). "To analyze the levels of selected genes from the grafted human cancer cells, we designed species-specific qPCR primers for FOXP2, E-cadherin, and PHF2 of human and mouse." (PMID 33718155, 2021). "Our findings demonstrated a novel role of the miR-23b/27b/24 cluster in cell migration through targeting FOXP2, with potential implications for the development of microRNA-based therapy targeted at inhibiting cancer migration." (PMID 31936744, 2020). "For the past few years, researches have demonstrated the involvement of FOXP2 in oncogenesis, but it exerts opposite function in different cancers." (PMID 31824836, 2019). "Parallel comprehensive studies in other cancer types will help to better understand the roles of FOXP2 in oncogenesis." (PMID 29725501, 2018). "Throughout this review we have focused upon published reports involving FOXP2 dysregulation during cancer progression." (PMID 29725501, 2018). "Subsequently, this cascade converged on and repressed the expression of FOXP2 promoting cancer stem cell (CSC) and metastatic traits." (PMID 29725501, 2018). "We have collated observations from cancer databases on genomic lesions involving genes in the vicinity of FOXP2 in section 5.2 (see further)." (PMID 29725501, 2018). "ABCA6 and ABCG2, which are direct targets of FOXP2 in its regulatory network, exhibit aberrant expression in various cancers." (PMID 30360388, 2018). "ABCA6 and ABCG2 showed aberrant expression in different types of cancers and are direct FOXP2 target genes." (PMID 29725501, 2018). "FOXP2 thus belongs to a domain featuring cancer epigenome consolidation, priming clustered genes for generalized dysregulation through alteration of chromatin accessibility to transcription." (PMID 29725501, 2018). "Aberrant expression of FOXP2 was detected in diverse cancer types, including up- or down-regulated FOXP2 levels depending on the type of cancer, with few discrepancies between peer-reviewed studies and ProteinAtlasDatabase." (PMID 29725501, 2018). "Analysis of individually validated genes upregulated by FOXP2 using IPA revealed cancer as the top listed disease." (PMID 29725501, 2018). "Thirdly, in the long-term phase of the longitudinal study, high FOXP2 levels were found to correlate with relapse frequency of ERG-negative cancers." (PMID 29725501, 2018). "We exploited these data to draft a putative network of FOXP2-dependent target genes modified before or during cancer progression." (PMID 29725501, 2018). "Transcriptomic profiling of tumor cells has led to the discovery that cancer stem cells which display a severe malignant and highly metastatic phenotype expressed reduced FOXP2 levels with regards to normal cells." (PMID 29725501, 2018). "Upregulation of FOXP2 reversed AGAP2-AS1 knockdown-induced suppression on cancer growth." (PMID 39124865, 2024). "FOXP2 is expressed in various cancers and acts as an oncogene or suppressor in carcinogenesis." (PMID 36331719, 2023).
cancer (continued). "We next investigated whether the low expression of FOXP2, which is the most often mutated FOX gene in cancers, was due to its high mutation burden." (PMID 37401400, 2023). "FOXP2 expressed in multiple adult tissues and might act as either a tumor-suppressor or a tumor-stimulator depending on the type of cancers studied, presenting a challenge for targeting FOXP2 as a universal target in cancer therapy." (PMID 33718155, 2021). "The expression of FOXP2 itself was also regulated in cancer cells." (PMID 33718155, 2021). "Thus, the upregulation of FOXP2 expression in NTMs and confirms that hypomethylation have a significantly positive effect on FOXP2 expression in non-cancer group." (PMID 34322159, 2021). "The decrease of TWIST levels during the MET progression might also explain the up-regulation of FOXP2 in MET of the Cholera Toxin-induced cancer cells." (PMID 33718155, 2021). "Recently, FOXP2 was also shown to be involved in cancer development." (PMID 31936744, 2020). "We also explored the interaction between FOXP2 and the genes involved in the progression of cancer." (PMID 29725501, 2018). "Other genes related to FOXP2 that may be involved in cancer drug resistance by drug efflux according to IPA analysis of FOXP2 targets include: FOXO1, RRAS, MAPK3, PIK3R1, MRAS and PIK3CB." (PMID 29725501, 2018). "In cancer and epithelial cells exposed to carcinogens, cell survival and proliferation are regulated by such inflammatory response as well as from apoptotic pathways involving targets of FOXP2 including: Cyclin D, c-MYC and BCL2." (PMID 29725501, 2018). "FOXP2 mainly acts as a repressor and has a dual role in oncogenesis and cancer progression." (PMID 30360388, 2018). "Screening canonical molecular pathways for putative targets of FOXP2 we observe that from angiogenesis/neovasculogenesis to glucose metabolism and apoptosis, different cancer-promoting physiological processes might be impacted by FOXP2 dysregulation." (PMID 29725501, 2018). "Cis-regulatory control of FOXP2: a target for cancer signaling cascades?" (PMID 29725501, 2018). "We categorized these cancer conditions according to FOXP2 levels, relative to healthy tissues." (PMID 29725501, 2018). "Several databases display FOXP2 expression levels in other cancer types, which we elected to mention, because no associated articles were available at the time of preparation of this review." (PMID 29725501, 2018). "Along the same line of analysis, the rare case reports involving loss of heterozygosity of FOXP2 have so far been associated with neuro-developmental disorders but not with cancer." (PMID 29725501, 2018). "The ProteinAtlasDatabase displays FOXP2 immunodetection within twenty surveyed cancer types." (PMID 29725501, 2018). "Interestingly, FOXP2 levels were reported to significantly correlate with cancer cells proliferative activity." (PMID 29725501, 2018). "The present manuscript reviews the features of FOXP2 genomic context, its transcripts, its protein isoforms and targets, and data that substantiate the notion of a critical contribution of FOXP2 to cellular barriers against cancer progression." (PMID 29725501, 2018). "We explored the possibility that FOXP2 might also exert a role during a later phase of the oncogenic process, in the active elimination of therapeutic agents by cancer cells." (PMID 29725501, 2018). "Further functional links between FOXP2 and cancer through dysregulation of other signaling processes may warrant examination." (PMID 29725501, 2018). "Putative molecular involvement of FOXP2 during cancer initiation, maintenance and metastasis processes may relate to FOXP2 ability to differentially modify the expression of target genes linked to several signaling pathways (see section 2.3.1)." (PMID 29725501, 2018). "Centromeric regulatory elements place FOXP2 under cancer-prone signaling cascades." (PMID 29725501, 2018).